PHGDH (phosphoglycerate dehydrogenase)
Description:
Catalyzes the reversible oxidation of 3-phospho-D-glycerate to 3-phosphonooxypyruvate, the first step of the phosphorylated L-serine biosynthesis pathway. Also catalyzes the reversible oxidation of 2-hydroxyglutarate to 2-oxoglutarate and the reversible oxidation of (S)-malate to oxaloacetate.
Synonyms: 3-PGDH; SERA; PGDH; PDG; 3PGDH; HEL-S-113; NLS; NLS1; PGAD; PGD; PHGDHD
Tractability: Small molecule: a structure with a bound ligand is known; a high-quality ligand is known; it has a high-quality binding pocket. Antibody: the Human Protein Atlas places it where antibodies can reach. PROTAC: UniProt records ubiquitination sites on it; ubiquitination databases record sites on it; its protein half-life has been measured; a small molecule that binds it is known.
Target class: Enzyme; Oxidoreductase
Chemical probes: BI-4916 (high quality), BI-4924 (high quality), BI-9593 (high quality)
Gene: Protein-coding gene on chromosome 1 (119,648,411 to 119,744,227, forward strand). Ensembl gene ENSG00000092621.
Subcellular location (Human Protein Atlas): Cytosol; Nucleoplasm; Plasma membrane; Mitotic spindle; Primary cilium
Pathways (Reactome):
Metabolism: Serine metabolism
Gene Ontology:
Molecular function: phosphoglycerate dehydrogenase activity; protein binding; electron transfer activity; (R)-2-hydroxyglutarate (NAD+) dehydrogenase activity; L-malate dehydrogenase (NAD+) activity; NAD binding; oxidoreductase activity, acting on the CH-OH group of donors, NAD or NADP as acceptor
Biological process: L-serine biosynthetic process; brain development
Cellular component: extracellular exosome; cytosol
Genetic constraint (gnomAD): Loss-of-function variants: 44 observed, 48.98 expected, observed/expected ratio (o/e) 0.9, 90% interval 0.7 to 1.15. The upper end of that interval is the gene's LOEUF score, 1.15, which puts it in group 5 of 6, group 1 being the genes least tolerant of losing a copy. Missense variants: 599 observed, 686.29 expected, observed/expected ratio (o/e) 0.87, 90% interval 0.81 to 0.93. Synonymous variants: 260 observed, 287.26 expected, observed/expected ratio (o/e) 0.91, 90% interval 0.82 to 1.
Gene-disease validity (ClinGen):
ClinGen rates the evidence that PHGDH causes each of these diseases.
neurometabolic disorder due to serine deficiency (autosomal recessive): Definitive. Serine-deficiency syndrome is a very rare infantile-onset potentially treatable neurometabolic disorder characterized clinically by microcephaly, neurodevelopmental disorders and seizures.
Homologues: Orthologues: chimpanzee PHGDH (99% identical), macaque PHGDH (99% identical), mouse Phgdh (95% identical), rat Phgdh (94% identical), rabbit PHGDH (94% identical), guinea pig PHGDH (91% identical), pig PHGDH (91% identical), zebrafish phgdh (59% identical), tropical clawed frog phgdh (55% identical), Caenorhabditis elegans phdh-1 (32% identical), Drosophila melanogaster CG6287 (32% identical). Paralogues in human: CTBP2 (22% identical), CTBP1 (21% identical), GRHPR (17% identical).
Diseases named in the same sentence as PHGDH in open-access papers:
PHGDH is named in the same sentence as 202 diseases in open-access papers, as found by Europe PMC text mining. Sharing a sentence is not in itself a finding about the gene and the disease. The quoted sentences say what the papers report.
breast carcinoma (176 papers, 2009 to 2026). "In breast cancer, the amplification of PHGDH and upregulation of ADHFE1 have been implicated in the accumulation of D-2HG." (PMID 39910592, 2025). "Certain breast cancers (especially ER−) depend on genomic amplification of PHGDH to divert glycolytic flux into serine and glycine metabolism and PHGDH-high breast cancer lines are more susceptible to Nampt inhibition." (PMID 39796638, 2024). "The upregulation of CHAC1 following PHGDH silencing has been implicated in breast cancer, and in AML; its overexpression is associated with high-risk prognosis and reduced overall survival." (PMID 38690164, 2024). "More recently, work also utilizing breast cancer models has suggested that heterogeneous or low PHGDH protein expression at the primary tumor site is associated with increased metastatic potential." (PMID 36276057, 2022). "describe a correlation between loss of phosphoglycerate dehydrogenase (PHGDH) expression in primary tumors of breast cancer patients and shortened metastasis-free survival." (PMID 36203456, 2022). "The overexpression of the gene encoding PHGDH has been identified in human cancers, particularly in breast cancers and melanomas, and PHGDH inhibition was reported to reduce proliferation." (PMID 33921788, 2021). "Amplification of the phosphoglycerate dehydrogenase (PHGDH) gene, encoding the first and limiting enzyme involved in de novo serine synthesis, was detected both in breast cancer and melanoma." (PMID 33499022, 2021). "PHGDH expression is observed frequently in ER-negative breast cancer, and increased PHGDH expression in breast cancer is associated with poor prognosis." (PMID 34552932, 2021). "Several studies have also implicated PHGDH in tumorigenesis in some cancers, such as breast cancer and melanoma." (PMID 34436421, 2021). "Several reports have shown that DNA amplification of PHGDH underlies the high expression of PHGDH in various types of cancers (melanoma, breast cancer, and clear cell renal cell carcinoma)." (PMID 32386122, 2020). "For instance, mutations or copy-number variation in genes such as phosphoglycerate dehydrogenase (PHGDH) have also been linked to promoting breast cancer." (PMID 31819196, 2020). "Li reported downregulation of PHGDH caused by overexpressing LncRNA PlncRNA-1 mediated cell apoptosis rate in breast cancer." (PMID 32894095, 2020). "High expression of PHGDH is also found to be associated with poor prognosis in breast cancer and lung adenocarcinomas." (PMID 30744688, 2019). "Genomic amplification of PHGDH at chromosome 1p was found to be the cause of its over-expression in melanoma and breast cancer." (PMID 31615983, 2019). "Regarding other AAs, phosphoglycerate dehydrogenase (PHGDH) is a metabolic enzyme used in serine synthesis, and overexpression of PHGDH has been associated with mortality of patients with breast cancer." (PMID 31885621, 2019). "More recent findings have extended these observations to reveal that PHGDH, the gene encoding PHGDH, is frequently amplified in melanoma and certain forms of breast cancer." (PMID 29568346, 2018). "Sustained proliferation of some melanoma and breast cancer cells has been associated to amplification of phosphoglycerate dehydrogenase (PHGDH), the enzyme catalyzing the first step of serine biosynthesis." (PMID 26733270, 2015). "It was reported that PHGDH expression and metastasis are closely associated in breast cancer." (PMID 38945960, 2024). "In breast cancer, higher PHGDH expression is associated with higher tumor grade and worse survival." (PMID 37444501, 2023). "Flux through this pathway can be important for the proliferation of some cancer cells, and the PHGDH gene is located in a region of focal genomic copy number gain that is associated with subsets of breast cancer and melanoma as well as cell lines derived from other cancer types." (PMID 31331318, 2019). "Up-regulation of PHGDH was associated with poor prognosis in breast cancer patients." (PMID 31615983, 2019).
breast carcinoma (continued). "Alterations in redox state may be relevant to PHGDH expression, as increased serine synthesis is associated with resistance to oxidative stress in melanoma and breast cancer." (PMID 31331318, 2019). "Subsequent studies showed significantly enhanced PHGDH expression in melanoma and breast cancer, indicating that these cancer types might be susceptible to treatment by PHGDH inhibition." (PMID 29568346, 2018). "Thus, we hypothesize that a breast cancer subset with high expression of enzymes associated with serine metabolism (PHGDH and PSPH) could present with an aggressive behavior." (PMID 24979213, 2014). "Moreover, two independent studies published while revising this manuscript suggest that PHGDH amplification could be another oncogenic driver mutation in breast cancer and melanoma, which would sensitize cells to inhibition of Phgdh." (PMID 22438825, 2012). "Previous studies have established its role in post-translational modification of metabolic enzymes including PFKFB3, PKM2, and PHGDH, which collectively promote de novo fatty acid biosynthesis in breast cancer models." (PMID 41501793, 2026). "ESRP1 binding to the PHGDH 5′-UTR enhances transcript stability in therapy-resistant ER+ breast cancer, whereas eIF3i recognizes m6A marks to selectively promote PHGDH translation in colorectal cancer." (PMID 41486146, 2026). "Pro-Metastatic Functions of Low PHGDH Expression: TGF-β1 inhibition downregulating PHGDH yet promoting metastasis in breast cancer." (PMID 41486146, 2026). "KDM4B deficiency enriches promoter H3K36me3 to sustain breast cancer stemness, while SUMOylated NRF2 (K110) transcriptionally activates PHGDH to bolster antioxidant defenses in HCC." (PMID 41486146, 2026). "Conversely, low expression of PHGDH correlated with increased breast cancer metastasis, and highly vascularized tumors had lower PHGDH expression." (PMID 39567756, 2025). "Amplification of the PHGDH gene on chromosome 1p12 occurs in 6% and 40% of breast cancers and melanomas, respectively." (PMID 40265021, 2025). "Acetylation of PHGDH at the K58 site disrupts the interaction between the E3 ubiquitin ligase RNF5 and PHGDH, reducing PHGDH degradation and increasing enzyme stability, thereby promoting breast cancer cell proliferation." (PMID 39778006, 2025). "In melanoma and breast cancer, PHGDH gene copy number is significantly increased, supporting the notion that tumor cells upregulate endogenous SSP activity in response to metabolic stress." (PMID 41415540, 2025). "Serine is another amino acid that can be synthesized in breast cancer cells via the activity of the 3-phospho-glycerate dehydrogenase (PHGDH) enzyme, which is up-regulated in breast cancer." (PMID 40809180, 2025). "For example, in human breast cancer cells with PHGDH gene amplification, PHGDH knockout significantly reduced cell proliferation, an effect not rescued by excess serine supplementation in the culture medium." (PMID 41415540, 2025). "Collectively, these results showed that NAT10 and its downstream factors PHGDH/PSAT1 are crucial for the proliferation of metastatic breast cancer cells in the serine/glycine-limited environment." (PMID 40138393, 2025). "Inhibiting PHGDH has been shown to suppress the growth of several breast cancer cell lines, primarily by disrupting redox balance." (PMID 39859211, 2025). "The overexpression of PHGDH and PSAT1 is significantly associated with poor clinical outcomes and malignant phenotypes in breast cancer." (PMID 39973065, 2025). "Consistent with prior reports in OS and breast cancer, inhibition of PHGDH with NCT-503 suppressed the proliferation of OS cells without induction of cell death." (PMID 39934141, 2025).
breast carcinoma (continued). "The PHGDH inhibitor NCT-502 effectively hinders tumor advancement in breast cancer by facilitating ferroptosis." (PMID 39569390, 2025). "Breast cancer relies on Ser/Gly synthesis, with 6% of patient samples showing copy number gains of the phosphoglycerate dehydrogenase gene (PHGDH)." (PMID 40723225, 2025). "Phosphoglycerate dehydrogenase (PHGDH) is frequently amplified in breast cancer and melanoma samples and increases serine flux to support tumor growth." (PMID 40523311, 2025). "PHGDH was highly expressed in 11 of 13 metastases compared to the paired primary breast cancer tissues." (PMID 40138393, 2025). "Comparable results were noted in cell lines of breast cancer, indicating D-2HG accumulation was prominently regulated by PHGDH and D2HGDH in TNBC." (PMID 39910592, 2025). "Genetic or pharmacological inhibition of PHGDH by NCT-503 preferentially impaired the growth of PHGDH-amplified breast cancer cells in bone marrow-mimicking conditions and in intra-tibial xenograft models by inducing oxidative stress and nucleotide depletion." (PMID 41488002, 2025). "In MDA-MB-231 breast cancer cells, the enzyme 3-phosphoglycerate dehydrogenase (PHGDH), which catalyzes the first step in serine synthesis from the glycolytic intermediate 3-phosphoglycerate, is overexpressed under hypoxic conditions." (PMID 39859211, 2025). "Approximately 67% of breast cancers exhibit homogeneously high PHGDH expression, while 33% show heterogeneous or low expression." (PMID 39973065, 2025). "Inhibiting PHGDH using short hairpin RNA results in doxorubicin-induced oxidative stress and increases the sensitivity of breast cancer cells to doxorubicin." (PMID 39973065, 2025). "It has also shown that the heterogeneity of PHGDH expression is closely related to the dissemination and metastatic potential of breast cancer cells." (PMID 39973065, 2025). "Silencing PHGDH or PSAT1 in metastatic breast cancer cells inhibits their growth in the serine/glycine-limited condition, phenocopying the effects of NAT10 depletion." (PMID 40138393, 2025). "PKUMDL-WQ-2101 inhibits de novo serine synthesis in PHGDH-amplified breast cancer cell lines and shows anti-tumor activity, reducing the growth of MDA-MB-468 xenograft tumors in mice." (PMID 39973065, 2025). "For example, PHGDH overexpressing breast cancer cell lines require elevated NAD+ salvage pathway activity to meet the high demand for NAD+-dependent PHGDH activity." (PMID 38698089, 2024). "The degradation of PHGDH by ring finger protein 5 inhibited breast cancer cell growth, and the acetylation of PHGDH at K58 disrupted the interaction between ring finger protein 5 and PHGDH and promoted breast cancer cell proliferation." (PMID 38945960, 2024). "In various breast cancer cell lines, PHGDH expression was found to be highly dependent on hypoxia-inducible factor expression in a hypoxic environment." (PMID 38945960, 2024). "In other words, PHGDH inhibitors have a synergistic effect with chemotherapeutic drugs, suggesting their combination as an effective approach for treating breast cancer patients." (PMID 38945960, 2024). "One study showed that the E53 ubiquitin ligase ring finger protein 5 is essential for PHGDH protein degradation in breast cancer." (PMID 38945960, 2024). "In vivo, in lung metastases derived from breast cancer, rapamycin had an antitumor effect on reducing the tumor area only in PHGDH-overexpressing breast cancer group." (PMID 38945960, 2024). "In a recent study, it has been shown that low PHGDH expression potentiates metastatic dissemination in breast cancer." (PMID 38115544, 2024). "Breast cancer cells with elevated PHGDH expression also exhibit heightened serine synthesis, and inhibiting PHGDH significantly reduces cell proliferation and inhibits serine synthesis." (PMID 38945960, 2024).
breast carcinoma (continued). "Phosphoglycerate dehydrogenase (PHGDH) is an important rate-limiting enzyme in the endogenous serine synthesis pathway, which is highly expressed in various types of tumors (such as breast cancer, colorectal cancer, bladder cancer, etc)." (PMID 39612465, 2024). "It has been shown that the activity of enzymes such as phosphoserine aminotransferase 1 (PSAT1), phosphoglycerate dehydrogenase (PHGDH), and phosphoserine phosphatase, which catalyze the synthesis of serine de novo, have increased expression in breast cancer." (PMID 39852119, 2024). "The results showed higher PHGDH protein and mRNA expression in most breast cancer cells than in human normal mammary epithelial cells." (PMID 38710705, 2024). "ER-negative, basal-like breast cancers show increased expression of both PHGDH and nicotinamide phosphoribosyltransferase (NAMPT), the rate-limiting enzyme of NAD+ salvage, and are sensitive to NAMPT inhibition." (PMID 38698089, 2024). "Several studies of breast cancer and melanoma have shown that gene amplification contributes to PHGDH overexpression and that PHGDH expression can be upregulated by the transcription factor NRF2 in non-small cell lung cancer." (PMID 38710705, 2024). "PHGDH has been reported to be a potential target in many cancers including breast cancer, colorectal cancer, and melanoma." (PMID 37387559, 2023). "Previous studies have reported that PHGDH is frequently overexpressed in a number of different cancer types including breast cancer, NSCLC, and melanoma, due to gene amplification, transcription, or post-translational modification." (PMID 36823188, 2023). "Triple-negative breast cancer cells exposed to doxorubicin undergo metabolic remodeling, resulting in increased serine synthesis regulated by PHGDH." (PMID 37187454, 2023). "Disrupting serine synthesis can be detrimental for some tumors because decreasing PHGDH expression impairs the growth of subcutaneous lung cancer and breast cancer xenografts." (PMID 37187454, 2023). "Studies have shown that the expression of PHGDH is elevated in some patients with breast cancer, pancreatic cancer and lung cancer, and most patients with elevated PHGDH expression show poor prognosis." (PMID 36994237, 2023). "An interesting point is the heterogeneity of PHGDH in primary and metastatic tumors in breast cancer." (PMID 36998464, 2023). "Exposure of PHGDH-kd ER+ breast cancer cells to cytotoxic chemotherapy (carboplatin or doxorubicin) leads to increased mitochondrial ROS and blocks the enrichment of CSCs induced by chemotherapy." (PMID 37187454, 2023). "Although a number of reports indicate that PHGDH plays a key role in breast cancer tumorigenesis, progression, and metastasis, the conclusions remain controversial." (PMID 37444501, 2023). "And in primary breast cancer, the upregulation of PHGDH and PSAT1 is also significantly related to the shortening of overall survival time and the malignancy of breast cancer." (PMID 36998464, 2023). "Recent studies reveal that PHGDH is frequently overexpressed to activate serine synthesis and promote tumor growth in several types of cancer, including breast cancer, non-small-cell lung cancer (NSCLC), and melanoma." (PMID 36823188, 2023). "Semenza and colleagues reported that knockdown of PHGDH in the MDA-MB-231 human breast cancer cell line increased the sensitivity to chemotherapeutic drugs and suppressed lung-metastatic ability." (PMID 37444501, 2023). "In terms of mechanism, the decreased expression of kinase C zeta (PKC-ζ) in bone-derived breast cancer cells led to the upregulation of PHGDH, PSAT1 and PSPH, consequently promoted the utilization of glutamine through serine biosynthesis." (PMID 36998464, 2023). "Possemato reported that the PHGDH gene is in a genomic region of recurrent copy number gain in breast cancer, and the PHGDH protein levels are elevated in 70% of estrogen receptor-negative breast cancers." (PMID 37664062, 2023).